NCBP1 (nuclear cap binding protein subunit 1)
Description:
Component of the cap-binding complex (CBC), which binds cotranscriptionally to the 5'-cap of pre-mRNAs and is involved in various processes such as pre-mRNA splicing, translation regulation, nonsense-mediated mRNA decay, RNA-mediated gene silencing (RNAi) by microRNAs (miRNAs) and mRNA export. The CBC complex is involved in mRNA export from the nucleus via its interaction with ALYREF/THOC4/ALY, leading to the recruitment of the mRNA export machinery to the 5'-end of mRNA and to mRNA export in a 5' to 3' direction through the nuclear pore. The CBC complex is also involved in mediating U snRNA and intronless mRNAs export from the nucleus. The CBC complex is essential for a pioneer round of mRNA translation, before steady state translation when the CBC complex is replaced by cytoplasmic cap-binding protein eIF4E. The pioneer round of mRNA translation mediated by the CBC complex plays a central role in nonsense-mediated mRNA decay (NMD), NMD only taking place in mRNAs bound to the CBC complex, but not on eIF4E-bound mRNAs. The CBC complex enhances NMD in mRNAs containing at least one exon-junction complex (EJC) via its interaction with UPF1, promoting the interaction between UPF1 and UPF2. The CBC complex is also involved in 'failsafe' NMD, which is independent of the EJC complex, while it does not participate in Staufen-mediated mRNA decay (SMD). During cell proliferation, the CBC complex is also involved in microRNAs (miRNAs) biogenesis via its interaction with SRRT/ARS2 and is required for miRNA-mediated RNA interference. The CBC complex also acts as a negative regulator of PARN, thereby acting as an inhibitor of mRNA deadenylation. In the CBC complex, NCBP1/CBP80 does not bind directly capped RNAs (m7GpppG-capped RNA) but is required to stabilize the movement of the N-terminal loop of NCBP2/CBP20 and lock the CBC into a high affinity cap-binding state with the cap structure. Associates with NCBP3 to form an alternative cap-binding complex (CBC) which plays a key role in mRNA export and is particularly important in cellular stress situations such as virus infections. The conventional CBC with NCBP2 binds both small nuclear RNA (snRNA) and messenger (mRNA) and is involved in their export from the nucleus whereas the alternative CBC with NCBP3 does not bind snRNA and associates only with mRNA thereby playing a role only in mRNA export. NCBP1/CBP80 is required for cell growth and viability.
Synonyms: CBP80; NCBP; Sto1
Tractability: Small molecule: a drug acting on it is in phase 2 or 3 trials; a structure with a bound ligand is known. PROTAC: UniProt records ubiquitination sites on it; ubiquitination databases record sites on it; its protein half-life has been measured.
Gene: Protein-coding gene on chromosome 9 (97,633,448 to 97,673,748, forward strand). Ensembl gene ENSG00000136937.
Subcellular location: Nucleus; Cytoplasm
Subcellular location (Human Protein Atlas): Cytosol; Nucleoplasm
Pathways (Reactome):
Metabolism of RNA: Nonsense Mediated Decay (NMD) enhanced by the Exon Junction Complex (EJC); Nonsense Mediated Decay (NMD) independent of the Exon Junction Complex (EJC); Nuclear RNA decay; Processing of Capped Intron-Containing Pre-mRNA; Processing of Intronless Pre-mRNAs; SLBP Dependent Processing of Replication-Dependent Histone Pre-mRNAs; SLBP independent Processing of Histone Pre-mRNAs; Transport of Mature mRNA Derived from an Intronless Transcript; Transport of Mature mRNA derived from an Intron-Containing Transcript; Transport of the SLBP Dependant Mature mRNA; Transport of the SLBP independent Mature mRNA; mRNA 3'-end processing; mRNA Capping; mRNA Polyadenylation; mRNA Splicing - Major Pathway; mRNA Splicing - Minor Pathway; snRNP Assembly
Disease: Abortive elongation of HIV-1 transcript in the absence of Tat; Dengue Virus-Host Interactions; Formation of HIV elongation complex in the absence of HIV Tat; Formation of HIV-1 elongation complex containing HIV-1 Tat; Formation of the HIV-1 Early Elongation Complex; Signaling by FGFR2 IIIa TM
Gene expression (Transcription): Formation of RNA Pol II elongation complex; Formation of the Early Elongation Complex; RNA Polymerase II Pre-transcription Events; RNA Polymerase II Transcription Termination; RNA polymerase II transcribes snRNA genes
Developmental Biology: Regulation of expression of SLITs and ROBOs
Signal Transduction: FGFR2 alternative splicing
Gene Ontology:
Molecular function: molecular adaptor activity; protein binding; RNA 7-methylguanosine cap binding; RNA binding; mRNA binding; RNA cap binding
Biological process: 7-methylguanosine mRNA capping; defense response to virus; histone mRNA metabolic process; mRNA export from nucleus; mRNA metabolic process; mRNA transcription by RNA polymerase II; nuclear-transcribed mRNA catabolic process, nonsense-mediated decay; positive regulation of cell growth; positive regulation of mRNA 3'-end processing; positive regulation of mRNA splicing, via spliceosome; regulation of translational initiation; RNA catabolic process; snRNA export from nucleus; spliceosomal complex assembly; alternative mRNA splicing, via spliceosome; cap-dependent translational initiation; miRNA-mediated post-transcriptional gene silencing; mRNA 3'-end processing; mRNA splicing, via spliceosome; positive regulation of transcription elongation by RNA polymerase II; primary miRNA processing; regulation of mRNA processing; regulatory ncRNA-mediated post-transcriptional gene silencing; RNA splicing; RNA metabolic process
Cellular component: cytoplasm; cytosol; nuclear cap binding complex; nucleoplasm; nucleus; ribonucleoprotein complex; RNA cap binding complex
Genetic constraint (gnomAD): Loss-of-function variants: 8 observed, 71.26 expected, observed/expected ratio (o/e) 0.11, 90% interval 0.065 to 0.2. The upper end of that interval is the gene's LOEUF score, 0.2, which puts it in group 1 of 6, group 1 being the genes least tolerant of losing a copy. Missense variants: 478 observed, 779.93 expected, observed/expected ratio (o/e) 0.61, 90% interval 0.57 to 0.66. Synonymous variants: 250 observed, 265.28 expected, observed/expected ratio (o/e) 0.94, 90% interval 0.85 to 1.05.
Homologues: Orthologues: chimpanzee NCBP1 (100% identical), macaque NCBP1 (100% identical), dog NCBP1 (99% identical), pig NCBP1 (99% identical), rat Ncbp1 (98% identical), mouse Ncbp1 (98% identical), rabbit NCBP1 (97% identical), guinea pig NCBP1 (95% identical), tropical clawed frog ncbp1 (84% identical), Drosophila melanogaster Cbp80 (58% identical), Caenorhabditis elegans ncbp-1 (35% identical).